OCIAD2 (OCIA domain containing 2)
Description:
Has an essential role in the assembly of mitochondrial respiratory chain complex III. Is also required for STAT3 activation and plays a role in cell migration.
Synonyms: MGC45416
Tractability: PROTAC: ubiquitination databases record sites on it; its protein half-life has been measured.
Gene: Protein-coding gene on chromosome 4 (48,885,019 to 48,906,937, reverse strand). Ensembl gene ENSG00000145247.
Subcellular location: Endosome; Mitochondrion; Mitochondrion inner membrane
Subcellular location (Human Protein Atlas): Mitochondria
Gene Ontology:
Molecular function: protein binding
Biological process: cell migration; mitochondrial respiratory chain complex III assembly; endocytosis; hematopoietic stem cell homeostasis; positive regulation of receptor signaling pathway via JAK-STAT
Cellular component: endosome; mitochondrial inner membrane; mitochondrion; Golgi apparatus; lysosome
Genetic constraint (gnomAD): Loss-of-function variants: 7 observed, 3.23 expected, observed/expected ratio (o/e) 2.17. That is too few expected variants to judge how well the gene tolerates losing a copy. Missense variants: 36 observed, 38.59 expected, observed/expected ratio (o/e) 0.93, 90% interval 0.71 to 1.23. Synonymous variants: 10 observed, 11.42 expected, observed/expected ratio (o/e) 0.88, 90% interval 0.54 to 1.48.
Homologues: Orthologues: chimpanzee OCIAD2 (98% identical), macaque OCIAD2 (97% identical), pig OCIAD2 (87% identical), mouse Ociad2 (84% identical), rat Ociad2 (84% identical), dog OCIAD2 (84% identical), rabbit OCIAD2 (82% identical), tropical clawed frog ociad2 (48% identical), zebrafish ociad2 (36% identical), Drosophila melanogaster asrij (26% identical). Paralogues in human: OCIAD1 (31% identical).
Diseases named in the same sentence as OCIAD2 in open-access papers:
OCIAD2 is named in the same sentence as 26 diseases in open-access papers, as found by Europe PMC text mining. Sharing a sentence is not in itself a finding about the gene and the disease. The quoted sentences say what the papers report.
lung adenocarcinoma (6 papers, 2019 to 2025). A carcinoma that arises from the lung and is characterized by the presence of malignant glandular epithelial cells. "According to our previous proteogenomicstudy of the Taiwan CancerMoonshot cohort, OCIAD2 was identified as highly expressed in patientswith lung adenocarcinoma and strongly associated with unfavorableprognosis." (PMID 40690206, 2025). "Collectively, these findings demonstrated thatelevated levels of OCIAD2 expression contribute to metabolic reprogrammingtoward glycolytic dependence in lung adenocarcinoma." (PMID 40690206, 2025). "These findingssuggest that OCIAD2 promotes cancer progression through metabolicreprogramming, highlighting the role of OCIAD2 as a potential biomarkerand therapeutic target for lung adenocarcinoma." (PMID 40690206, 2025). "This highlights the criticalneed to examine the proteogenomic data of lung adenocarcinoma patientsto elucidate the precise function of the invasive neuroblastoid OCIAD2." (PMID 40690206, 2025). "Overall,our study sheds light on the role of OCIAD2 in the cancer progressionof lung adenocarcinoma." (PMID 40690206, 2025). "This may partly explain the absenceof correlation with established clinicopathologic factors in our cohortand further support the potential role of OCIAD2 as an independentprognostic biomarker in lung adenocarcinoma." (PMID 40690206, 2025). "These findingsprovide valuable insights into the underlying mechanisms mediatedby OCIAD2 and highlight its potential as a negative prognostic biomarkerin lung adenocarcinoma." (PMID 40690206, 2025). "The concordance of findings at both the RNA and proteinlevels emphasized that the presence of OCIAD2 might be a criticalfactor influencing cell motility pathways in lung adenocarcinoma acrossdiverse omics analyses." (PMID 40690206, 2025). "Taken together, our findings suggest that OCIAD2 maypromote lung adenocarcinoma progression through metabolic reprogramming." (PMID 40690206, 2025). "OCIAD2 is mainly located on the mitochondrial membrane of lung adenocarcinoma cells." (PMID 39179991, 2024). "The methylation status of OCIAD2 may be a useful prognostic indicator in patients with hepatoblastoma and lung adenocarcinoma." (PMID 39445005, 2024). "And OCIAD2 is also highly expressed in lung adenocarcinoma but also ovarian mucinous tumors." (PMID 37409245, 2023). "Furthermore,the consistent observations in both our cohort and public data setsindicated that OCIAD2 might serve as a universal prognostic factoracross different populations, emphasizing its value as an importantbiomarker in lung adenocarcinoma." (PMID 40690206, 2025). "Notably, OCIAD2 and PARP 1, which are inversely related to many immune cells, coincide with the results that these two genes are associated with the poor prognosis of lung adenocarcinoma." (PMID 37409245, 2023). "Overall, our study proposed a novel oncogenic role for the poorlycharacterized protein, OCIAD2, suggesting its involvement in cancerprogression through the regulation of metabolic reprogramming betweenthe OXPHOS and glycolysis pathways in lung adenocarcinoma." (PMID 40690206, 2025). "Therefore, OCIAD2 may be an effective therapeutic target for lung adenocarcinoma." (PMID 39179991, 2024). "In our previous studies, we found that IGBP1, OCIAD2 and DDAH2 showed high expression in lung adenocarcinoma and their expression appeared to be epigenetically regulated." (PMID 30899432, 2019).
lung carcinoma (5 papers, 2021 to 2025). "OCIAD2 may indirectly exert tumor-promoting activities, and its downregulation led to the loss of mitochondrial structure and an overall decrease in proliferation and invasion in lung cancer." (PMID 39201394, 2024). "Given that the deregulationof cellular energetics is a key hallmark of cancer, it is essential to further explore the functional impactof OCIAD2 on mitochondrial bioenergetics in lung cancer cells." (PMID 40690206, 2025). "Takentogether, the cellular functional assays demonstrated that the downregulationof the cellular component of OCIAD2 inhibits motility, invasion, andcolony formation of lung cancer cells." (PMID 40690206, 2025). "Additionally, several cell functional assays wereconducted to characterize the phenotypic changes in lung cancer cellsgiven the OCIAD2 shRNA treatment, including MTT assay, colony formationassay, transwell migration, and invasion assays." (PMID 40690206, 2025). "However, the expression difference of FABP4 and OCIAD2 genes in H1299 lung cancer cells was insignificant, but both showed a trend of increase." (PMID 37409245, 2023). "The expression of OCIAD2 was highly expressed in the invasive adenocarcinoma than in the in situ adenocarcinoma in lung cancer, whereas the expression level is significantly reduced in liver cancer and gastric stroma carcinoma, when compared with that in the corresponding normal tissues." (PMID 35646656, 2022). "Besides, associated with OCIAD2, immunocytochemical staining for SFN could also increase diagnostic sensitivity for lung cancers." (PMID 33742334, 2021). "We can estimate the expression level of HUB genes, and it is clear that two HUB genes, OCIAD2 and PARP 1, have higher expression in lung cancer samples, while the remaining HUB genes have more expression in normal samples." (PMID 37409245, 2023).
ovarian carcinoma (4 papers, 2018 to 2024). A malignant neoplasm originating from the surface ovarian epithelium. "OCIAD2, part of the ovarian cancer immune response antigen (OCIA) domain family, promotes tumor metastasis by enhancing STAT3 activation and cell migration." (PMID 39445005, 2024). "OCIAD2 belongs to the ovarian cancer immune response antigen (OCIA) domain family, which consists of 154 amino acids." (PMID 37409245, 2023). "The Ovarian Carcinoma Immunoreactive Antigen domain (OCIAD) - containing proteins OCIAD1/Asrij and OCIAD2, are implicated in several cancers and neurodegenerative diseases." (PMID 29743632, 2018). "On the other hand, OCIAD2 expression is low in the ovary whereas ovarian carcinomas have increased expression of OCIAD2." (PMID 29743632, 2018).
breast carcinoma (2 papers, 2018 to 2026). "In the ieu-a-1126 cohort, genes with causal relationships to breast cancer included GNB2, HADH, OAS2, OCIAD2, P4HA2, and PAFAH1B3." (PMID 41424847, 2026). "In the ebi-a-GCST90018799 cohort, genes with causal relationships to breast cancer included NOP58, OCIAD2, P4HA2, PEMT, and PNPLA2." (PMID 41424847, 2026).
glioblastoma (2 papers, 2022 to 2025). The most malignant astrocytic tumor (WHO grade IV). "OCIAD2 proteins are a conserved class of proteins in eukaryotes, with increased expression in cancerous tumors; they are downregulated in hepatocellular carcinoma, gastric carcinoma, glioblastoma, and chronic lymphocytic leukemia." (PMID 39466086, 2025).
glioma (2 papers, 2022 to 2026). A benign or malignant brain and spinal cord tumor that arises from glial cells (astrocytes, oligodendrocytes, ependymal cells). "In glioma, the role and function of OCIAD2 also remain controversial." (PMID 35646656, 2022). "have reported that OCIAD2 is overexpressed in gliomas that have a poor prognosis." (PMID 35646656, 2022).
hepatoblastoma (2 papers, 2022 to 2024). Hepatoblastoma (HB) is a malignant hepatic tumor and is the most common pediatric liver cancer. "Limited genome-wide methylation analysis by HM450 found that differentially methylated genes were involved with liver cell differentiation and cancer, and four tumor suppressor genes (GPR180, MST1R, OCIAD2, and PARP6) were potentially related to progression in hepatoblastomas." (PMID 36212481, 2022).
hepatocellular carcinoma (2 papers, 2014 to 2025). A malignant tumor that arises from hepatocytes. "Applied the approach on GSE42357 and GDS3634 expression data from NCBI, and the paths with the lowest cost were picked out as the responsible possible molecular mechanisms between TGFβ and OCIAD2 in hepatocellular carcinoma (HCC) samples and prostate cancer cell lines." (PMID 24949437, 2014).
Alzheimer disease (1 paper, 2020). A progressive, neurodegenerative disease characterized by loss of function and death of nerve cells in several areas of the brain leading to loss of cognitive function such as memory and language. "While little is known about the function of OCIAD1, a homolog designated as OCIAD2 has been identified as a modulator of γ-secretase, an enzyme that stimulates the production of amyloid β in the early stage of Alzheimer’s disease." (PMID 32697788, 2020).
bladder cancer (1 paper, 2024). "OCIAD2 has been associated with prognosis in bladder cancer patients and shows potential in immunotherapy." (PMID 39445005, 2024).
bronchioloalveolar carcinoma (1 paper, 2019). A well or moderately differentiated morphologic variant of lung adenocarcinoma characterized by tumor growth along the alveolar structures without stromal, vascular, or pleural invasion. "OCIAD2 was highly expressed in adenocarcinoma mixed subtype with bronchioloalveolar carcinoma component and was associated with improved prognosis." (PMID 31262330, 2019).
prostate carcinoma (1 paper, 2014). A carcinoma that arises from epithelial cells of the prostate gland. "As DU-145 is an AR-independent cell lacking AR protein expression, the predicted path from AR to OCIAD2 in prostate cancer needs more support of more biological experiments." (PMID 24949437, 2014).
tumor (17 papers, 2014 to 2026). "OCIAD2 has been associated with tumor formation, though its involvement in LUAD regulation is uncertain." (PMID 39466086, 2025). "In this study, we identify OCIA domain containing 2 (OCIAD2) as a central mediator of chemoresistance and tumor progression in HNSCC." (PMID 41655222, 2026). "In nude mice, tumor growth was inhibited by silencing hsa_circ_0001492, while knockdown of miR-145-5p and overexpression of OCIAD2 promoted the growth of LUAD tumors." (PMID 39466086, 2025). "The effects of hsa_circ_0001492, miR-145-5p, and OCIAD2 on LUAD tumor development were examined using xenograft mouse models and immunohistochemistry tests." (PMID 39466086, 2025). "OCIAD2 was highly expressed in tumor tissues in 95.5% of lungadenocarcinoma patients in our cohort, with elevated expression correlatingwith worse survival." (PMID 40690206, 2025). "Reduced expression of OCIAD2 by DNA hypermethylation was reported to play an important role in HCC tumor growth and invasion." (PMID 36212481, 2022). "Additionally, both knockdown of miR-145-5p and overexpression of OCIAD2 significantly attenuated the inhibitory effect of silencing hsa_circ_0001492 on tumor growth and resulted in significantly higher Ki-67 positivity." (PMID 39466086, 2025). "We hereby speculate that downregulated OCIAD2 expression in tumor microenvironment facilitates deregulated TGFβ signaling." (PMID 24949437, 2014). "In this study, a bioinformatics approach was developed, and it demonstrated that the function-unknown protein ovarian carcinoma immunoreactive antigen-like protein 2 (OCIAD2) is probably regulated by TGFβ and AR signals in the tumor EMT process." (PMID 24949437, 2014). "With pbMOO approach, the functional unknown protein OCIAD2 was also enrolled into a signal pathway “TGFβ1- TGFβR1- SMAD2/3- SMAD4- AR-OCIAD2” in tumor and adjacent microenvironment." (PMID 24949437, 2014). "Another research indicated that the four novel tumor suppressor candidates including GPR180, MST1R, OCIAD2, and PARP6 were potentially useful molecular markers for predicting poor prognosis in HB patients." (PMID 33312943, 2020). "ERβ, a known tumor suppressor in COAD, may regulate OCIAD2 expression, potentially leading to mitochondria-related apoptosis." (PMID 39201394, 2024). "Knockdown and overexpression studies showed that OCIAD2 is essential for STAT3 activation and cell migration, which could contribute to its role in tumor metastasis." (PMID 29743632, 2018). "Additionally, PTTG1 may correlate with the BLCA tumor microenvironment and exert transcriptional activity by targeting CHEK2, OCIAD2, UBE2L3, and ZNF367 in BLCA tissue." (PMID 35768832, 2022). "Interestingly, of the few genes that, via sPLS-DA, were predicted to contribute to tumor regression at certain stage-to-stage interfaces—including DAPK2, PLAC9, ABCB9, MELTF, CTHRC1, and OCIAD2, testing for LUAD patient survivability via AK4 combination resulted in a negative prognosis." (PMID 34940617, 2021).
cancer (11 papers, 2014 to 2025). A tumor composed of atypical neoplastic, often pleomorphic cells that invade other tissues. "The association between miR-145-5p and hsa_circ_0001492/ovarian carcinoma immunoreactive antigen domain 2 (OCIAD2) was validated using a dual luciferase experiment." (PMID 39466086, 2025). "Further, loss of OCIAD2 function promotes cancer progression by increasing activation of the PI3K/Akt pathway." (PMID 29743632, 2018). "Metacore pathway analysis of OCIAD2-associatedDEGs derived fromtwo public data sets indicated enrichment in various aspects of cellmovement, including cytoskeleton remodeling and cell adhesion, bothof which are known to play important roles in cancer progression." (PMID 40690206, 2025). "Our findings in Figure demonstrated that elevated levels of OCIAD2expression might promote cancer progression in lung adenocarcinomavia cell motility-related processes; however, the underlying mechanismsof the OCIAD2-mediated signaling pathways remained unclear." (PMID 40690206, 2025). "OCIAD1 has been shown to regulate energy metabolism in human pluripotent stem cells and suppression of OCIAD2 led to a reduction in mitochondria and the downregulation of cellular growth in cancer cell lines." (PMID 39364696, 2025). "First, the mRNA expression levels of OCIAD2 in 23lung cancer cell lines were measured by reverse transcription quantitativereal-time polymerase chain reaction (RT-qPCR)." (PMID 40690206, 2025). "MetaCore analysis of the proteomic data from the same cohortindicated that OCIAD2 promotes cancer progression, which was furthervalidated through in vitro functional assays, includingtranswell migration, invasion, and colony formation assays." (PMID 40690206, 2025). "OCIAD2 is an immunoreactive protein with an unclear function, the expression of which is diverse in different cancers." (PMID 35646656, 2022). "As Asrij activates STAT39 and OCIAD2 is implicated in several cancers where STAT3 is active, we checked for any functional homology between the OCIAD proteins by testing the ability of different regions of OCIAD2 to bring about STAT3 activation." (PMID 29743632, 2018). "It is noteworthy that while OCIAD2 expression is higher in kidney, liver and brain relative to other tissues sampled, carcinomas of the liver and brain have significantly reduced OCIAD2 expression." (PMID 29743632, 2018). "After verifying the biological meaning of the low-cost paths, the signal TGFβ1- TGFβR1- SMAD2/3- SMAD4- AR-OCIAD2 was discovered and explained TGFβ's stimulation on OCIAD2 expression in cancer." (PMID 24949437, 2014). "The results supported the ideathat OCIAD2 may promote cancer progression by modulating the processof cellular movement and invasion." (PMID 40690206, 2025). "In previous function assays, OCIAD2 was shown to be essential for the activation of signal transducer and activator of transcription 3 and cell migration, which suggested that OCIAD2 may contribute to the metastasis of cancer cells." (PMID 35768832, 2022). "The expression pattern of OCIAD2 varies across different mouse tissues and carcinomas." (PMID 29743632, 2018). "Thus, tissue-specific differences in OCIAD2 expression levels co-relate inversely with its status in carcinomas." (PMID 29743632, 2018). "Notably,the expression of OCIAD2 varies across different cancer types." (PMID 40690206, 2025). "Similarly, OCIAD2, UBE2L3, and ZNF367 also displayed intimate association with cancer development." (PMID 35768832, 2022). "The remaining eight target genes (CFL1, FNBP4, NDUFB3, OCIAD2, PLIN3, POU2AF1, RAC1, TMEM141) presented a combined influence in five or fewer cancer types." (PMID 39201394, 2024). "In non-cancerous cells, OCIAD2 also interacts with and regulates STAT3 activation and cell migration, which is important in several developmental and immune processes as well as cancer." (PMID 29743632, 2018).
OCIAD2 also shares sentences with these, for which no sentence is quoted: adenocarcinoma (2 papers); liver cancer (2); anaplastic astrocytoma (1); cervical cancer (1); chronic lymphocytic leukemia (1); gastric carcinoma (1); in situ adenocarcinoma (1); multiple myeloma (1); neurodegenerative disease (1); ovarian mucinous tumors (1); Pleural effusion (1); type 2 diabetes (1).